ALG3 (ALG3 alpha-1,3- mannosyltransferase)
Diseases named in the same sentence as ALG3 in open-access papers (continued):
Sharing a sentence is not in itself a finding about the gene and the disease.
breast carcinoma (continued). "Our results suggest that ALG3 may serve as a potential radiosensitive marker, and an effective target to decrease radioresistance by regulating glycosylation of TGFBR2 in breast cancer." (PMID 33931075, 2021). "However, we did not observe significant correlation between ALG3 expression levels and endocrine therapy or anti-Her-2 therapy in breast cancer patients (data not shown)." (PMID 38329424, 2024). "In the present study, our results demonstrated that ALG3 was remarkably upregulated in radioresistant breast cancer tissue, which predicted poor clinicopathological characteristics and OS, and poor local recurrence-free survival (LRFS) in breast cancer patients." (PMID 33931075, 2021).
acute myeloid leukemia (6 papers, 2020 to 2022). Acute myeloid leukemia (AML) is a group of neoplasms arising from precursor cells committed to the myeloid cell-line differentiation. "The interaction between FTX and miR-342 was also validated in acute myeloid leukemia cells, resulting in the upregulation of another miRNA target, the ALG3 mannosyltransferase, thus contributing to drug resistance in acute myeloid leukemia." (PMID 35054794, 2022). "Recently, ALG3 has been reported to promote chemotherapy resistance by inducing mannosylation in acute myeloid leukemia." (PMID 33931075, 2021). "Moreover, FTX could regulate drug resistance of adriamycin against acute myeloid leukemia cells by competitively binding to miR-342 and altering ALG3 expression." (PMID 33817286, 2020). "In general, cancer cells have abnormal oligosaccharide chains; thus, involvement of ALG3 was reported in squamous cell cervical cancer, acute myeloid leukemia (AML), head and neck squamous cell carcinoma, non-small cell lung cancer, and oral squamous cell carcinoma." (PMID 36430241, 2022).
esophageal squamous cell carcinoma (6 papers, 2021 to 2024). Esophageal squamous cell carcinoma (ESCC) is a type of esophageal carcinoma (EC) that can affect any part of the esophagus, but is usually located in the upper or middle third. "Upregulation of ALG3 promoted the progression of cervical cancer and non–small-cell lung cancer and was proven to be associated with lymph node metastasis in esophageal squamous cell carcinoma." (PMID 35899200, 2022). "According to several reports, ALG3 is upregulated in squamous cell cervical cancer as well as esophageal squamous cell carcinoma and is responsible for inducing resistance to drugs in myeloid leukemia." (PMID 38329424, 2024). "In esophageal squamous cell carcinoma, ALG3 was shown to be a viable treatment target, and its overexpression was revealed to be closely related to lymph node metastasis." (PMID 38329424, 2024). "Upregulation of ALG3 promoted the metastasis of esophageal squamous cell cancer to lymph nodes and the proliferation of cervical cancer cells." (PMID 35774357, 2022). "ALG3 upregulation is related to lymph node metastasis of esophageal squamous cell carcinoma and the proliferation of cervical cancer cells." (PMID 34650911, 2021).
hepatocellular carcinoma (4 papers, 2020 to 2025). A malignant tumor that arises from hepatocytes. "To research the role of ALG3 in hepatocellular carcinoma, first, we explored the ALG3 expression on online public human hepatocellular carcinoma datasets of the GEO and TCGA databases." (PMID 35782861, 2022). "Our study planned to explore the clinical implication and potential function of ALG3 in hepatocellular carcinoma." (PMID 35782861, 2022). "Therefore, ALG3 plays a critical role not only in the initiation and progression of hepatocellular carcinoma but also in modulating the immune microenvironment." (PMID 40475760, 2025).
lymph node metastasis (3 papers, 2021 to 2022). "ALG3 expression is higher in NSCLC tissues than in normal tissues and is associated with a higher T stage, lymph node metastasis, tissue differentiation, and prognosis." (PMID 34650911, 2021). "Moreover, ALG3 as a class of glycosyltransferases promotes the proliferation and radiosensitivity of cancer cells and is related with poor prognosis and lymph node metastasis." (PMID 34195087, 2021).
non-small cell lung carcinoma (3 papers, 2022). A group of at least three distinct histological types of lung cancer, including non-small cell squamous cell carcinoma, adenocarcinoma, and large cell carcinoma. "ALG3 contributes to the malignancy of non-small-cell lung cancer (NSCLC) and is negatively regulated by miR-98-5p." (PMID 36555445, 2022). "High ALG3 expression, negatively regulated by miR-98-5p, exerted a pro-carcinogenic effect by promoting EMT, thus leading to poor prognosis in non–small-cell lung cancer." (PMID 35899200, 2022).
triple-negative breast carcinoma (3 papers, 2024 to 2025). An invasive breast carcinoma which is negative for expression of estrogen receptor (ER), progesterone receptor (PR), and human epidermal growth factor receptor 2 (HER2). "In a study on triple-negative breast cancer (TNBC), high ALG3 expression was found to correlate with poor clinical prognosis and immune evasion." (PMID 40475760, 2025).
carbohydrate deficient glycoprotein syndrome type IV (2 papers, 2019 to 2023). "Defects in ALG3 have been associated with a congenital disorder of glycosylation type Id characterized by severe neurological involvement." (PMID 38022516, 2023).
epilepsy (2 papers, 2019 to 2025). A brain disorder characterized by episodes of abnormally increased neuronal discharge resulting in transient episodes of sensory or motor neurological dysfunction, or psychic dysfunction. "Epilepsy-associated genes (TPP1, BCKDK, ALG3, and PACS1) were upregulated and enriched in PZ and showed higher expression in the TLE as compared with the healthy control scRNA data." (PMID 39541170, 2025).
autoimmune disease (1 paper, 2020). A disorder resulting from loss of function or tissue destruction of an organ or multiple organs, arising from humoral or cellular immune responses of the individual to their own tissue constituents. "Besides PMM2-CDG, three reports of autoimmune diseases have been associated with the ALG gene family (eosinophilic esophagitis in an ALG1-CDG patient with a severe phenotype, and psoriasis in an ALG3-CDG and an ALG6-CDG patient)." (PMID 32635232, 2020).
developmental delay (1 paper, 2021). "Presumably because of poor compliance due to young age at examination and developmental delay available ophthalmic data in ALG3-CDG are limited." (PMID 34090370, 2021).
hyperinsulinism (1 paper, 2023). Abnormally high levels of insulin in the blood. "The entities reported to be associated with hyperinsulinism are PMM2-CDG (CDG1a), MPI-CDG (CDG1b), ALG3-CDG (CDG1d), and PGM1-CDG (CDG1t) (reviewed by 97, 98)." (PMID 37065762, 2023).
Hypoglycemia (1 paper, 2020). A decreased concentration of glucose in the blood. "Other CDG in which hypoglycemia has been reported are DOLK‐CDG, ALG6‐CDG, ALG3‐CDG, and ALG12‐CDG." (PMID 32071842, 2020).
Infertility (1 paper, 2024). "Taken together, these results indicate mut-16 and alg-3; alg-4 mutants have analogous thermosensitive sperm-based infertility phenotypes." (PMID 38967024, 2024).
intellectual disabilities (1 paper, 2025). "ALG3-CDG patients display developmental and intellectual disabilities, muscular hypotonia, cerebral malformations, neurological features such as epileptic seizures, cardiac defects, facial and body dysmorphism, and metabolic dysfunction including refractory hypoglycemia." (PMID 40789468, 2025).
liver cancer (1 paper, 2022). An epithelial or non-epithelial malignant neoplasm that arises from the liver. "Based on our studies, we could speculate that ALG3 may participate in the occurrence and development of liver cancer by regulating and recruiting the expression of immuno-infiltrating cells." (PMID 35782861, 2022).
liver disease (1 paper, 2021). "The authors classified CDG based on liver involvement into two main groups: one with predominant/isolated liver involvement (MPI-CDG, CCDC115-CDG, TMEM199-CDG, ATP6AP1-CDG) and the other associated with liver disease (PMM2-CDG, ALG1-CDG, ALG3-CDG, ALG8-CDG, ALG9-CDG, PGM1-CDG)." (PMID 34291020, 2021).
ovarian carcinoma (1 paper, 2022). A malignant neoplasm originating from the surface ovarian epithelium. "This study highlights ALG3 as a potential diagnostic biomarker and prospective therapeutic target for ovarian cancer." (PMID 36231102, 2022). "In addition, ALG3 facilitated metastatic potential by inducing the α1,3-mannosylation of uPAR, whereas uPAR N-glycosylation site mutation and the inhibition of α1,3-mannosylation by ALG3 downregulation suppressed ovarian cancer metastasis." (PMID 36231102, 2022). "Moreover, to clarify the relationship between ALG3 expression and long-term prognosis, we used the Kaplan-Meier plotter database to analyze the association between ALG3 mRNA expression and prognosis in ovarian cancer patients." (PMID 36231102, 2022). "However, the role of ALG3 in ovarian cancer progression and the underlying molecular mechanism is unknown." (PMID 36231102, 2022). "Taken together, our data demonstrate that ALG3/α1,3-mannosylation is necessary for ovarian cancer cells to maintain their metastatic malignancy in the mouse abdominal cavity." (PMID 36231102, 2022). "The results suggested that overall survival in patients with high expression of ALG3 in ovarian cancer was significantly shorter than those in the low-expression group (log-rank test p < 0.001)." (PMID 36231102, 2022). "From the TCGA database (N = 88, OC = 426), we identified that the expression of ALG3 was the highest among ALG members in ovarian cancer tissues compared with that in normal ovarian tissues." (PMID 36231102, 2022). "The results showed that ALG3 cDNA promoted the adhesion of ovarian cancer cells to HPMCs, and ALG3 siRNA decreased it." (PMID 36231102, 2022). "Our results showed that ALG3 overexpression promoted stemness, proliferation and adhesion to peritoneal mesothelial cells in ovarian cancer cells." (PMID 36231102, 2022). "The in vitro and in vivo results also revealed that decreased α1,3-mannosylation by ALG3 suppressed ovarian cancer stemness and peritoneal metastasis." (PMID 36231102, 2022). "The results also showed elevated ALG3 in both the ovarian cancer tissue slides and ovarian cancer tissue microarray compared with that in the normal ovary." (PMID 36231102, 2022). "Collectively, our results revealed that elevated α1,3-mannosylation and ALG3 were related to metastatic ovarian cancer and a poor prognosis and promoted the proliferation, stemness and peritoneal metastasis of ovarian cancer cells." (PMID 36231102, 2022). "An in vivo ovarian cancer mouse model also indicated that elevated α1,3-mannosylation by ALG3 drives ovarian metastasis." (PMID 36231102, 2022). "Longitudinal imaging demonstrated that the amount of ascites was high in the mouse ovarian cancer group (OC) compared with that in the ALG3 downregulation group (si-ALG3) and GNA blockade group (GNA-)." (PMID 36231102, 2022). "The effect of ALG3 on the ability of ovarian cancer cells to adhere to mesothelial cells was also detected." (PMID 36231102, 2022). "The downregulation of ALG3 decreased the proliferation, stemness and peritoneal metastasis of ovarian cancer cells." (PMID 36231102, 2022). "ALG3 was also correlated with the poor prognosis of ovarian cancer patients, according to survival analysis." (PMID 36231102, 2022). "We investigated the role of ALG3 in ovarian cancer peritoneal metastasis by EMT, transwell migration/Matrigel invasion and scratch assays, as well as an adhesion assay." (PMID 36231102, 2022). "The results indicate that ALG3 overexpression stimulated the proliferation and stemness of ovarian cancer cells." (PMID 36231102, 2022). "Based on the fact that α1,3-mannosylation on the b branch of Man5GlcNAc2-PP-Dol is catalyzed by ALG3, we next detected ALG3 expression in normal ovarian and ovarian cancer tissues." (PMID 36231102, 2022).
ovarian carcinoma (continued). "The results showed that the level of ALG3/α1,3-mannosylation was higher in human ovarian cancer tissues compared with normal ovarian tissues, as measured by Lectin chip, Western blot and Lectin blot analyses, as well as ovarian tissue microarray analysis." (PMID 36231102, 2022). "The transwell assay showed that co-transfection with ALG3 cDNA and uPAR cDNA promoted the migration and invasion ability of ovarian cancer cells." (PMID 36231102, 2022). "However, the pathological significance of ALG3 and its regulatory mechanism in ovarian cancer metastasis is unclear." (PMID 36231102, 2022). "In the present study, we observed that the levels of α1,3-mannosylation and ALG3 were significantly upregulated in ovarian cancer tissues compared with normal ovarian tissues, which was closely related to metastatic potential and the poor prognosis of the patients." (PMID 36231102, 2022). "Collectively, these data demonstrate that ALG3 was abnormally highly expressed in ovarian cancer, and the altered expression of ALG3 would explain the changes in mannosyl glycan structures associated with the metastatic potential and poor prognosis in ovarian cancer." (PMID 36231102, 2022). "Silencing ALG3 reduced the peritoneal metastasis of ovarian cancer." (PMID 36231102, 2022). "Furthermore, decreased ALG3 suppressed ascites formation and the peritoneal metastasis of ovarian cancer cells in mice." (PMID 36231102, 2022). "Furthermore, the ovarian cancer tissues showed stronger expression of ALG3 on Western blots." (PMID 36231102, 2022). "However, whether N-glycosylation, especially α1,3-mannosylation by ALG3, is associated with ovarian cancer metastasis is not known." (PMID 36231102, 2022). "To gain insight into changes in mannosyltransferases (ALGs), which have been found (ALG1, ALG2, ALG3, ALG9, ALG11 and ALG12) in ovarian cancer, we queried publicly available transcriptomic data, including Gene Expression Omnibus (GEO, GSE18520) and The Cancer Genome Atlas (TCGA) datasets." (PMID 36231102, 2022). "In addition, ALG3 was found to increase the α1,3-mannosylation of uPAR and enhance its interaction with and activation of ADAM8, thus promoting ovarian cancer metastasis." (PMID 36231102, 2022). "However, the effect and the glycobiological mechanism of ALG3/α1,3-mannosylation in ovarian cancer metastasis are not clear." (PMID 36231102, 2022).
pancreatic cancer (1 paper, 2025). "Directly targeting glycosyltransferases such as B3GNT3 in pancreatic cancer or ALG3 to induce immunogenic ferroptosis represents a promising strategy, particularly given the ability of ALG3 inhibition to enhance immunotherapy responses." (PMID 41008983, 2025).
paraganglioma (1 paper, 2025). A benign or malignant neoplasm arising from paraganglia located along the sympathetic or parasympathetic nerves. "In contrast, ALG3 expression was downregulated in pheochromocytomas and paragangliomas." (PMID 40475760, 2025).
polycystic kidneys (1 paper, 2017). "Defects in the N-linked glycosylation genes ALG3, ALG8, and ALG9, as well as the O-linked glycosylation gene B3GALTL, variably result in polycystic kidneys, cleft lip or palate, polycystic ovaries, and abnormal development of the brain including the corpus callosum." (PMID 28344780, 2017).
sterility (1 paper, 2012). "Accordingly, loss of ALG-3/ALG-4 class 26G RNAs results in male-associated sterility at non-permissive temperatures due to defects in sperm activation that are thought to arise from target dysregulation." (PMID 22548001, 2012).
cancer (19 papers, 2020 to 2025). A tumor composed of atypical neoplastic, often pleomorphic cells that invade other tissues. "Similar studies have shown that ALG3 is highly expressed in various cancer types and is closely associated with changes in the immune microenvironment." (PMID 40475760, 2025). "Because cancer stem cell often contributes to drug-resistance, we thus explored the association between ALG3 gene expression and drug resistance." (PMID 38329424, 2024). "The link between ALG3 and a patient’s treatment susceptibility to anti-cancer medications was investigated in this research for the first time." (PMID 38329424, 2024). "In COAD and ESCA, ALG3 expression was inversely linked to TMB but was linked to TMB in other 12 forms of cancers in a positive manner." (PMID 38329424, 2024). "Inhibition of asparagine-linked glycosylation 3 (ALG3) stimulates cancer cell immunogenic ferroptosis to potentiate immunotherapy." (PMID 36710875, 2022). "Moreover, while ALG3 overexpression promotes cancer progression, loss-of-function ALG3 mutations result in severe clinical manifestations in congenital disorders of N-glycosylation (ALG3-CDG)." (PMID 40789468, 2025). "Collectively, the expression of ALG3 was shown to be positively linked to the expression of genes associated with immune checkpoints in the majority of cancers, which supported the assumption that ALG3 might be effective in tumor immunotherapy." (PMID 38329424, 2024). "Additionally, immune biomarkers had also been linked to ALG3 expression in most kinds of cancer." (PMID 38329424, 2024). "To investigate the expression of ALG3 in various solid tumors, we downloaded transcriptomic data from the TCGA public database and analyzed the expression differences between cancer tissues and their corresponding normal tissues across multiple tumor types." (PMID 40475760, 2025). "In human cancers, ALG3 is amplified in a variety of lineages, including lung, breast, ovarian, and esophageal cancers." (PMID 40789468, 2025). "N-glycosylation of 4F2hc by B3GNT3, immunogenic ferroptosis induced by ALG3 deficiency, and the GAG-mediated lipoprotein uptake pathway exemplify the sophisticated ways in which cancer cells exploit the glycosylation machinery to evade ferroptotic cell death." (PMID 41008983, 2025). "The therapeutic implications of ALG3 targeting are particularly compelling because ALG3 inhibition synergizes with immune checkpoint blockade therapy in mouse cancer models." (PMID 41008983, 2025). "Identifying the precise identity of the glycome and the glycoproteome regulated by PI3K/AKT/ALG3 is predicted to uncover a new layer on the role of PI3K/AKT in cancer." (PMID 40789468, 2025). "We also discovered that cancer patients having a high level of ALG3 exhibited a lower probability of benefiting from immunotherapy." (PMID 38329424, 2024). "The cancer stem cell-like characteristics evaluated by mRNA (RNAss) and DNA methylation (DNAss) exhibited a substantial inverse link to ALG3, as shown by the analysis results." (PMID 38329424, 2024). "It has been discovered that ALG3 expression levels are usually elevated in nearly all cancers in contrast with that in normal tissues." (PMID 38329424, 2024). "Paired t-test was used to detect differences in ALG3 expression between cancer and neighboring samples, and ALG3 expression was found to be upregulated in cancer.The ROC curve showed that ALG3 had a good diagnostic efficiency for cancer (AUC = 0.741)." (PMID 39287231, 2024). "ALG3 was shown to have varying degrees of relationship with RNAs and DNAs, depending on the kind of cancer." (PMID 38329424, 2024). "Tissue microarrays constructed using 31 LUAD and 28 paraneoplastic samples were used and immunohistochemistry was used to validate ALG3 expression in cancer and neighboring cancers." (PMID 39287231, 2024). "Nonetheless, further investigation is warranted to shed light on the clinical value of ALG3 and its function in pan-cancer." (PMID 38329424, 2024).